PTPN14 (protein tyrosine phosphatase non-receptor type 14)
Diseases named in the same sentence as PTPN14 in open-access papers (continued):
Sharing a sentence is not in itself a finding about the gene and the disease.
neuroblastoma (continued). "Altogether, these results show that PTPN14 is involved in neuroblastoma cell migration and invasion without affecting cell proliferation." (PMID 31806880, 2020). "Our results showed an increase in neuroblastoma cell migration and invasion in the absence of any effect on stathmin levels, indicating that PTPN14 and stathmin did not act in a feedback regulatory loop in the PTPN14-depleted cells." (PMID 31806880, 2020). "The identification of PTPN14 and PTPN21 direct substrates is necessary to fully understand the role of these non-receptor PTPs in neuroblastoma." (PMID 34957126, 2021). "Collectively, these results indicate that PTPN14 and stathmin do not interact in a feed-forward manner and the expression levels of PTPN14 regulate the YAP/Hippo signalling pathway in a neuroblastoma cell line-dependent manner." (PMID 31806880, 2020). "However, using another neuroblastoma cell line SH-SY5Y/TGL, our results showed no significant alteration in YAP nuclear translocation and CYR61 mRNA expression in PTPN14-depleted SH-SY5Y/TGL cells compared with the control." (PMID 31806880, 2020).
colorectal cancer (8 papers, 2013 to 2023). A primary or metastatic malignant neoplasm that affects the colon or rectum. "And mutated PTPN14 is suggested to be a tumor suppressor gene for colorectal cancer, regulating cellular pathways that are appropriate for therapeutic intervention." (PMID 32536826, 2020). "Previous studies on the mutational analysis of the tyrosine phosphatase gene superfamily in human cancers identified 83 somatic mutations in six PTPs (PTPRF, PTPRG, PTPRT, PTPN3, PTPN13, PTPN14), affecting 26% of colorectal cancers and a smaller fraction of lung, breast and gastric cancers." (PMID 27833130, 2016). "The first of these linking PTPN14 to cancer began with a screen of the coding exons of all 87 members of the PTP super family in 18 colorectal cancers." (PMID 27240404, 2016). "Overall, levels of pY128 p130Cas, which could be favorably decreased by PTPN14, could be a predictive marker for patients’ response to Dasatinib treatment in colorectal cancer." (PMID 27240404, 2016). "Together with the finding that PTPN14 loss can induce aberrant acini formation in MCF-10A cells, these results indicate a potential tumor suppressive role for PTPN14 in human cells, in agreement with previous reports of PTPN14 loss of heterozygosity (LOH) in colorectal cancer." (PMID 23613971, 2013). "An early indication that PTPN14 might have tumor suppressor activity comes from an analysis of somatic mutations in colorectal cancer, in which 87 PTP genes were sequenced and just 6, including the gene coding for PTPN14, were frequently mutated in those tumors." (PMID 27651363, 2016). "In another study, it was found that PTPN14 was correlated with TNM stage and N stage in colorectal cancer." (PMID 34712552, 2021). "For colorectal cancer (CRC), PTPN2, PTPN21 and PTPN22 levels were correlated with incidence; expression of PTPN5, PTPN12, and PTPN14 was correlated with TNM stage and N stage; high PTPN5 or PTPN7 expression was associated with increased hazards of death." (PMID 32536826, 2020).
gastric cancer (7 papers, 2020 to 2023). A primary or metastatic malignant neoplasm involving the stomach. "In conclusion, we first demonstrated the function and the underlying molecular mechanism of PTPN14 in gastric cancer." (PMID 36898991, 2023). "In order to pursue the underlying molecular mechanism of PTPN14 enhancing gastric cancer progression, we performed a comparative proteomic analysis." (PMID 36898991, 2023). "To evaluate the diagnostic value of PTPN14 in gastric cancer, we analyzed the receiver operating characteristic curve." (PMID 36898991, 2023). "In order to explore the underlying mechanism of PTPN14 increased expression level in gastric cancer, we designed a dual luciferase reporter assay." (PMID 36898991, 2023). "High expression of PTPN14 is associated with the cTNM stage, N stage, and poor prognosis in gastric cancer." (PMID 36898991, 2023). "However, the roles and underlying molecular mechanisms of PTPN14 in gastric cancer are poorly understood." (PMID 36898991, 2023). "At present, the research on PTPN14 in gastric cancer is rarely reported and remains to be further explored." (PMID 36898991, 2023). "Immunohistochemistry analysis showed that the PTPN14 expression level was increased in gastric cancer tissues compared with paired normal adjacent tissues." (PMID 36898991, 2023). "To explore the function of PTPN14 in gastric cancer, we established and identified three stable cell lines." (PMID 36898991, 2023). "Gastric cancer patients with higher PTPN14 expression obtained a significantly shorter relapse-free survival time than patients with lower PTPN14 expression." (PMID 36898991, 2023). "Consistent with the online database, the overall survival time of gastric cancer patients with PTPN14 high expression level was shorter than patients with PTPN14 low expression level." (PMID 36898991, 2023). "However, the function and underlying mechanism of PTPN14 in gastric cancer remain unclear." (PMID 36898991, 2023). "Taken together, PTPN14 promotes gastric cancer cell proliferation, migration, and invasion by PI3K/AKT/mTOR pathway." (PMID 36898991, 2023). "The survival curve analysis showed that gastric cancer patients with higher PTPN14 expression had a shorter survival time." (PMID 36898991, 2023). "In this research, we combined sample validation, cellular, and molecular approaches to explore the function of PTPN14 in gastric cancer." (PMID 36898991, 2023). "Sample validation revealed that PTPN14 was highly expressed in gastric cancer, especially with lymph node metastasis (LNM)." (PMID 36898991, 2023). "In summary, our results illustrated the function of PTPN14 in gastric cancer and demonstrated the potential mechanisms." (PMID 36898991, 2023). "The Kaplan–Meier Plotter online database indicated that PTPN14 expression level was related to gastric cancer prognosis." (PMID 36898991, 2023). "In summary, the FERM domain of PTPN14 is the key domain in promoting gastric cancer cell proliferation, migration, and invasion." (PMID 36898991, 2023). "Further research indicated that PTPN14 promoted gastric cancer cell proliferation, migration, and invasion via the FERM domain." (PMID 36898991, 2023). "By IHC staining and scoring, we found that PTPN14 was upregulated in gastric cancer, especially with LNM." (PMID 36898991, 2023). "Analyses of the relationship between circ_PRRX1 and PTPN14 showed that circ_PRRX1 is able to positively control PTPN14 levels via sequestering miR-3064-5p, consequently intensifying doxorubicin resistance in gastric cancer." (PMID 35055115, 2022). "For instance, CircPRRX1 was shown to promote doxorubicin resistance in gastric cancer by inhibiting miR-3064-5p and enhancing protein tyrosine phosphatase, non-receptor type 14 (PTPN14) signaling." (PMID 34672237, 2021). "The expression of PTPN14 could fairly distinguish gastric cancer tissues from normal tissues, with the area under the curve of 0.784 (95% confidence interval = 0.754–0.815)." (PMID 36898991, 2023).
gastric cancer (continued). "The expression level of PTPN14 could help pathologists to distinguish gastric cancer tissues from normal gastric tissues, indicating the diagnostic value of PTPN14 in gastric cancer." (PMID 36898991, 2023). "CCK-8 and EDU assays showed that PTPN14 overexpression could promote gastric cancer cell proliferation and PTPN14 knockdown could inhibit gastric cancer cell proliferation." (PMID 36898991, 2023). "Our research illustrated the vital roles of PTPN14 in gastric cancer." (PMID 36898991, 2023). "In addition, we collected five gastric cancer cell lines and detected PTPN14 expression level by western blot." (PMID 36898991, 2023). "In summary, PTPN14 promotes the PI3KA/AKT/mTOR pathway in gastric cancer." (PMID 36898991, 2023). "Meanwhile, overexpressing PTPN14 could promote gastric cancer cell migration and invasion in MKN-45 and BGC-823 cells." (PMID 36898991, 2023). "In gastric cancer, PTPN14 promoted the PI3K/AKT/mTOR pathway." (PMID 36898991, 2023). "Furthermore, we analyzed the relationship between C/EBPβ expression level and PTPN14 expression level in gastric cancer from the TCGA database." (PMID 36898991, 2023). "Therefore, NFkB nucleus translocation was vital and necessary for PTPN14 to exert gastric cancer’s supporting role." (PMID 36898991, 2023). "Our research showed that PTPN14 was an unfavorable prognosis factor in gastric cancer." (PMID 36898991, 2023). "Finally, we established mice models to validate the function and the molecular mechanism of PTPN14 in gastric cancer." (PMID 36898991, 2023). "The transwell assay indicated that the knockdown of PTPN14 could suppress gastric cancer cell migration and invasion in AGS cells." (PMID 36898991, 2023). "We collected gastric cancer tissues and detected the expression of PTPN14." (PMID 36898991, 2023). "Taken together, PTPN14 is activated by C/EBPβ at the transcriptional level in gastric cancer." (PMID 36898991, 2023). "The online database indicated that PTPN14 may be related to the prognosis of gastric cancer patients." (PMID 36898991, 2023). "By overexpression or knockdown of PTPN14, we demonstrated that PTPN14 could promote gastric cancer proliferation, migration, and invasion." (PMID 36898991, 2023). "We found that TFA could eliminate the promoting effect of PTPN14 on gastric cancer proliferation, migration, and invasion." (PMID 36898991, 2023). "Moreover, PTPN14 has a positive regulatory effect on the migration and invasion of gastric cancer cells; inhibition of PTPN14 can reduce the epithelial-mesenchymal transition in gastric cancer cells." (PMID 36106167, 2022). "Finally, circPRRX1 strengthens doxorubicin resistance in gastric cancer by regulating miR-3064-5p/PTPN14 signaling." (PMID 35957898, 2022). "Additionally, PTPN14 overexpression can upregulate and downregulate the level of vimentin and caspase-3, respectively, in gastric cancer." (PMID 35055115, 2022). "In conclusion, PTPN14 may play as a tumor promoter in gastric cancer." (PMID 36898991, 2023). "Therefore, PTPN14 could promote gastric cancer cell proliferation, migration, and invasion in vitro." (PMID 36898991, 2023). "Furthermore, the FERM domain of PTPN14 was the key domain in gastric cancer promotion." (PMID 36898991, 2023). "In addition, we illustrated that CEBP/β (CCAAT enhanced binding protein beta) could transcriptionally activate PTPN14 expression in gastric cancer." (PMID 36898991, 2023). "In our research, the NFkB inhibitor could diminish the gastric cancer-prompting effect of PTPN14." (PMID 36898991, 2023). "However, there are very few studies illustrating the function of PTPN14 in gastric cancer." (PMID 36898991, 2023). "The online database indicated that PTPN14 may be a poor prognostic factor for gastric cancer." (PMID 36898991, 2023). "To illustrate the positive regulation of PTPN14 on PI3KA in vivo, we analyzed the correlation between PTPN14 expression level and PI3KA expression level in gastric cancer from the TCGA database." (PMID 36898991, 2023).
gastric cancer (continued). "Protein tyrosine phosphatase non-receptor type 14 (PTPN14) functions as an oncogenic factor by advancing the proliferation and migration of gastric cancer cells via triggering Hippo signaling." (PMID 35055115, 2022). "miR-217 induced the down-regulation of PTPN14 and inhibited the EMT in gastric cancer cells." (PMID 31793993, 2020). "Furthermore, the expression of PTPN14 in gastric cancer with LNM was elevated compared with gastric cancer tissues without LNM." (PMID 36898991, 2023). "However, PTPN14 could hardly distinguish gastric cancer patients with LNM from patients without LNM." (PMID 36898991, 2023).
pancreatic cancer (7 papers, 2016 to 2023). "PTPN14 encodes an inhibitor of the Yap oncoprotein and is involved in pancreatic cancer suppression." (PMID 34957301, 2021). "All these genes are upregulated in pancreatic cancer, and seven of them are significantly associated with unfavorable prognosis (MET, YAP1, PTPN14, EPS8, AHNAK, RALB, and AFAP1)." (PMID 34957301, 2021). "In the primary tumor, there was high expression of PTPN14, but this was significantly lower in the liver metastases, suggesting a role of PTPN14 in the metastatic process of pancreatic cancer." (PMID 27240404, 2016). "First, PTPN14 overexpression promoted YAP cytoplasmic localization and inhibition of proliferation in pancreatic cancer cells." (PMID 31448276, 2019). "Transcriptional profiling of fresh frozen tissue derived from primary tumor, tumor invasion front and liver metastases, after orthotopic implantation of the human pancreatic cancer cell line MiaPaca-2 in severe combined immunodeficiency (SCID) mice, revealed differential PTPN14 expression." (PMID 27240404, 2016).
acute liver failure (5 papers, 2020 to 2023). Rapid deterioration of liver function causing encephalopathy and coagulopathy. "In acute liver failure, PTPN14 aggravates the NFkB signaling pathway by promoting SOCS7 degradation." (PMID 36898991, 2023). "In addition, we observed altered phosphorylation on PTPN14, which has recently been demonstrated to initiate cytokine storm and aggravate acute liver failure by interacting with and targeting SOCS7, a negative regulator of NF-κB signaling pathway to proteasomal degradation." (PMID 35011700, 2022).
basal cell carcinoma (4 papers, 2016 to 2024). A carcinoma involving the basal cells. "Most recently, genetic profiling of 293 basal cell carcinomas (BCCs) found PTPN14 to be mutated in 23% of the cases." (PMID 27240404, 2016). "Basal cell carcinoma (BCC) is the nonviral cancer that is most clearly linked to PTPN14." (PMID 35170430, 2022).
lung cancer (4 papers, 2015 to 2022). A malignant neoplasm involving the lung. "A recent lung cancer transcriptome meta-analysis showed that several HIPPO pathway component (NF2, LATS1, PTPN14, YAP1, TAZ, TAOK, and FAT1) genes were found to fuse in lung carcinoma, and they were independent prognosis factors for low lung cancer survival." (PMID 36147635, 2022).
glioblastoma (3 papers, 2020 to 2024). The most malignant astrocytic tumor (WHO grade IV). "In addition, miR-4516 was identified as a novel oncogene by targeting PTPN14 in glioblastoma, and stromal loss of miR-4516 could promote FOSL1-dependent proliferation and malignancy of triple-negative breast cancer." (PMID 39737397, 2024). "MiR-4516 functions as a novel oncogene and predicts poor prognosis by targeting PTPN14 in human glioblastoma." (PMID 34998421, 2022).
intrahepatic cholangiocarcinoma (3 papers, 2015 to 2016). A carcinoma that arises from the intrahepatic bile duct epithelium in any site of the intrahepatic biliary tree. "The repression of PTPN14 could promote intrahepatic cholangiocarcinoma cell growth." (PMID 27517633, 2016).
lymphedema (3 papers, 2022 to 2025). Excess fluid collection in tissues, causing swelling. "Finally, homozygous loss-of-function mutations to PTPN14 cause choanal atresia and lymphedema (OMIM: 613611)." (PMID 35806420, 2022). "PTPN14 interacts with VEGFR-3, and its deletion in mice causes lymphatic hyperplasia with lymphedema." (PMID 35806420, 2022).
metastatic disease (3 papers, 2020 to 2024). "PTPN14 expression has shown a progressive decrease from normal breast tissue to metastatic tumors." (PMID 39189475, 2024). "The study underscores PTPN14 as a potential therapeutic target for metastatic TNBC, with the therapeutic strategy based on mRNA expression of PTPN14 demonstrating clinical application prospects in alleviating the burden of both primary tumors and metastatic disease." (PMID 39189475, 2024).
melanoma (2 papers, 2019 to 2020). A malignant, usually aggressive tumor composed of atypical, neoplastic melanocytes. "We show here for metastatic breast, colon, and melanoma cells that the overexpression of PTPN14 reduces CAV1 pY14, as well as CAV1-induced migration and invasion in vitro, and the metastasis promoting role of CAV1 in vivo." (PMID 32152405, 2020). "We corroborated by western blotting experiments that PTPN14 and CAV1 co-inmunoprecipitated in the presence of E-cadherin in B16F10 melanoma and other cancer cells." (PMID 32152405, 2020). "This study identifies CAV1 as a novel substrate for PTPN14, since the phosphatase co-immunoprecipitates with CAV1 in murine melanoma cells B16F10 that express E-cadherin and over expression of PTPN14 reduces the phosphorylation of CAV1 on Y14." (PMID 32152405, 2020).
metastatic cancer (2 papers, 2020). A carcinoma which has spread from the original site of growth to another anatomic site. "A recent study proved that PTPN14 suffices to inhibit migration and invasion of metastatic cancer cells." (PMID 32536826, 2020).
asthenozoospermia (1 paper, 2024). "In cases of asthenozoospermia, protein tyrosine phosphatase non-receptor type 14 (PTPN14) shows dysregulation, while cystatin-C (CST3) levels are reduced." (PMID 39685846, 2024).
atherosclerosis (1 paper, 2023). A disease characterized by the build-up of fatty material and calcium deposition in the arterial wall resulting in partial or complete occlusion of the arterial lumen. "Many studies showed that PTPN14 has different function, such as suppressing the occurrence and development of tumor, blunting the formation of atherosclerosis and promoting inflammation and fibrosis." (PMID 37363723, 2023).
bladder cancer (1 paper, 2022). "Bioinformatic database screening for bladder cancer followed by gene co-expression network analysis revealed six new genes (PPARD, CST4, CSNK1E, PTPN14, ETV6, and ADRM1) and several new miRNAs, including miR-124, as drivers in the development and progression of bladder cancer." (PMID 36362406, 2022).
breast tumor (1 paper, 2024). "PTPN14 protein expression level was higher in normal breast tissue compared to the primary breast tumor." (PMID 39189475, 2024).